PLIN5 (perilipin 5)
Diseases named in the same sentence as PLIN5 in open-access papers (continued):
Sharing a sentence is not in itself a finding about the gene and the disease.
Obesity (12 papers, 2019 to 2026). Accumulation of substantial excess body fat. "Of particular interest, Plin5-Tg mice were protected from diet-induced obesity in association with improved insulin sensitivity and glucose tolerance." (PMID 37150323, 2023). "Our study aimed to explore the underlying mechanisms by which leptin reduces the N6-methyladenosine (m6A) methylation of Plin5 through fat mass and obesity associated genes (FTO) and regulates the lipolysis." (PMID 34638947, 2021). "A study on obesity found that RES attenuated the expression level of PLIN5 in BAT and heart tissue, while increasing the expression of PLIN5 in skeletal muscle." (PMID 39232826, 2024). "Here we show that prolonged cardiomyopathy in Plin5-Tg mice strongly interferes with whole body energy homeostasis thereby counteracting HFD-induced obesity and maintaining glucose tolerance." (PMID 37150323, 2023). "Functionally, augmented adipose tissue sympathetic innervation followed by increased ß-adrenergic signaling and thermogenic activity counteracted the development of HFD-induced obesity in Plin5-Tg mice." (PMID 37150323, 2023). "The important role of BAT in obesity resistance of Plin5-Tg mice is further supported by the strongly increased expression of UCP1 and TH upon acute cold exposure, whereas UCP1 expression was unchanged at thermoneutrality." (PMID 37150323, 2023). "The similar phenotype of WT and Plin5-Tg mice at thermoneutrality further indicated that increased BAT thermogenesis counteracts obesity development even at room temperature." (PMID 37150323, 2023). "Our data also provide evidence that Plin5 is a new target for preventing and delaying the onset of myocardial hypertrophy in obesity and diabetes mellitus." (PMID 37667357, 2023). "Together, Plin5-Tg mice counteract diet-induced obesity via elevated lipolytic and thermogenic activity in adipose tissue at room temperature (and upon cold exposure) but not at thermoneutrality." (PMID 37150323, 2023). "Reduced HFD-induced obesity in Plin5-Tg mice is most likely the consequence of increased ß-adrenergic signaling and lipolysis in adipose tissue and stimulation of BAT thermogenesis triggered by impaired cardiac FA oxidation and cardiomyopathy." (PMID 37150323, 2023). "This provides a nutritional strategy for reducing pig backfat and improving meat quality, and it also brings hope for the treatment and prevention of human related diseases with obesity by regulating the expression of Plin5." (PMID 34638947, 2021). "By revealing the function of Plin5, we provide a target for the treatment of diseases related to obesity, such as T2D, in the future and also provide a basis for studying the interaction between LD and other organelles." (PMID 34638947, 2021). "To determine the effect of acute PLIN5 deficiency in BAT on glucose tolerance in the context of high-fat diet (HFD) induced obesity, we fed male or female mice with 60% HFD without Dox for 8 weeks and housed the mice at 23 °C." (PMID 41509390, 2026). "Together, Plin5-Tg mice upregulate lipolytic and thermogenic activity in adipose tissue in response to acute cold stress at 4 °C and most likely at room temperature as an attempt to maintain body temperature, thereby counteracting diet-induced obesity." (PMID 37150323, 2023). "To investigate whether an increased energy demand to maintain body temperature protects Plin5-Tg mice from diet-induced obesity, we next assessed the impact of HFD on systemic energy homeostasis at thermoneutrality." (PMID 37150323, 2023). "The biochemical pathways involved in obesity resistance in Plin5−/− mice may provide a potential direction for obesity treatment." (PMID 35401929, 2022). "Changes in cardiac energy catabolism in Plin5-Tg mice increased ß-adrenergic signaling, lipolytic, and thermogenic protein expression in adipose tissue ultimately counteracting HFD-induced obesity." (PMID 37150323, 2023).
Obesity (continued). "Consistently, PLIN5 protein expression in islets of HFD mice and ob/ob obesity mice significantly increased compared with that of control mice." (PMID 31384284, 2019). "This study clarified that leptin can regulate Plin5 M6A methylation by promoting FTO to affect the lipid metabolism and energy consumption, providing a theoretical basis for treating diseases related to obesity." (PMID 34638947, 2021). "Acute cold exposure further augmented ß-adrenergic signaling in Plin5-Tg mice, whereas housing at thermoneutrality did not protect Plin5-Tg mice from HFD-induced obesity albeit blood glucose and insulin levels remained low in transgenic mice." (PMID 37150323, 2023).
cardiac hypertrophy (11 papers, 2016 to 2025). "The deficiency of Plin5 exacerbates the progression of cardiac hypertrophy and heart failure induced by pressure overload, concurrently reducing cardiac lipid accumulation and upregulating the levels of PPARα and PGC-1α." (PMID 40166465, 2025). "In this study, we found that lactate accumulation due to Plin5 deficiency aggravated myocardial hypertrophy in leptin-deficient mice." (PMID 37667357, 2023). "We also explored the roles and mechanism of Plin5 deficiency in the development of myocardial hypertrophy in leptin-deficient mice, which are characterized by abnormal lipid metabolism." (PMID 37667357, 2023). "Our previous study showed that Plin5 deficiency exacerbated pressure overload-induced cardiac hypertrophy and heart failure by enhancing myocardial FAO and oxidative stress." (PMID 37667357, 2023). "In this study, no obvious morphological changes were observed in the hearts between Plin5-deficient and wild-type mice, but Plin5 deficiency significantly exacerbated myocardial hypertrophy." (PMID 37667357, 2023). "Moreover, we found that Plin5 deficiency-induced lactate accumulation aggravated myocardial hypertrophy in leptin-deficient mice." (PMID 37667357, 2023). "However, long-term HFD-mediated metabolic stress causes contractile dysfunction in Plin5-Tg mice, which emphasizes the importance of a carefully controlled dietary regime in patients with cardiac steatosis and hypertrophy." (PMID 37150323, 2023). "Thus, lactate acts as a new important messenger metabolite to stimulate myocardial hypertrophy in Plin5-deficient mice." (PMID 37667357, 2023). "Accordingly, we found modulation of Perilipin-5 driven by MS-444: its absence in murine cardiomyocytes can lead to impaired glucose utilization, subsequently contributing to the development of cardiac hypertrophy." (PMID 41467913, 2025). "Studies demonstrate that Plin5 overexpression promotes cardiac hypertrophy, leading to increased lipid droplet accumulation in cardiomyocytes and impaired mitochondrial function, thereby affecting cardiac systolic function." (PMID 40863131, 2025). "This study demonstrates that myocardial Plin5 plays crucial roles in maintaining the homeostasis of glucose and fatty acid oxidation, which provides an experimental basis for preventing myocardial hypertrophy in metabolic disorders." (PMID 37667357, 2023). "DAPA mediated Plin5/PPAR-α signaling axis to reduce vascular endothelial growth factor-induced cardiac hypertrophy in vivo and in vitro, while silting Plin5 can reverse the protective effect of this pathway." (PMID 35509833, 2022). "In the study, we investigated the protective effect of dapagliflozin on AAC-induced cardiac hypertrophy and its mechanism of involving activation of the Plin5/PPARα signaling axis." (PMID 34630108, 2021). "Subsequently, ELISA and qRT-PCR assays were used to detect the expressions of cardiac hypertrophy-related molecules and verify the effect of si-Plin5 and GW6471 on the protective effect of dapagliflozin." (PMID 34630108, 2021). "This indicates the involvement of Plin5 in the regulation of myocardial hypertrophy." (PMID 40166465, 2025). "This suggests a role for Plin5 in the regulation of myocardial hypertrophy." (PMID 40166465, 2025). "Similarly, Plin isoforms show differential regulation under physiological and pathological conditions, such as during pregnancy-induced cardiac hypertrophy in rats, where increased expression of Plin1, Plin2, and Plin5 is observed." (PMID 39859272, 2025). "A study observing Plin5 knockout mice found a significant increase in lactic acid accumulation, and it was proposed that Plin5 deficiency drives myocardial cell hypertrophic growth by inhibiting the MPC and directing glucose towards lactate metabolism, leading to severe myocardial hypertrophy." (PMID 40166465, 2025).
cardiac hypertrophy (continued). "As leptin-deficient mice are characterized by abnormal lipid metabolism and cardiac hypertrophy, we generated Plin5/leptin-double-knockout (DKO) mice and found that lactate levels were significantly elevated in the myocardia of Plin5/leptin-DKO mice compared with those of leptin-knockout mice." (PMID 37667357, 2023). "Cardiac-specific overexpression of the lipid-droplet protein perilipin 5 (Plin5) promotes cardiac hypertrophy, but it is unclear whether this response is beneficial." (PMID 36717246, 2023). "In summary, this study confirmed that Plin5 deficiency promoted lactate accumulation due to excessive NADH production from FAO in cardiomyocytes, which impaired insulin signalling and resulted in myocardial hypertrophy in leptin-deficient mice." (PMID 37667357, 2023). "MRI revealed a similar ejection fraction of Plin5-Tg mice compared to controls at the age of 4 months despite a signature of cardiac hypertrophy and adverse cardiac remodeling including an increase in LV mass, LV posterior wall thickness, and relative wall thickness in Plin5-Tg mice." (PMID 37150323, 2023). "This difference may be related to the inherent ability of the normal adult heart to handle the TG rate and Plin5-independent FA flux, which is a characteristic of cardiac hypertrophy." (PMID 35509833, 2022). "Both in vivo and in vitro experiments have confirmed that DAPA could mediate the Plin5/PPARα signaling axis to play a protective role in inhibiting cardiac hypertrophy." (PMID 34630108, 2021). "Considering the molecular mechanism of Plin5 and PPARα in cardiac hypertrophy, we hypothesized that DAPA might mediate the protective effect of Plin5/PPARα signaling axis." (PMID 34630108, 2021). "Furthermore, we demonstrated an inhibitory role of DAPA on cardiac hypertrophy by activating Plin5/PPARα signaling cascades in the myocardium." (PMID 34630108, 2021). "Whether myocardial Perilipin 5 actions are adaptive in cardiac hypertrophy, for example in the context of pressure overload, remains to be determined." (PMID 27554864, 2016). "In addition, deficiency of perilipin 5 (PLIN5), a lipid droplet-associated protein that maintains the balance between lipolysis and lipogenesis, was found to irritate TAC-induced myocardial hypertrophy and heart failure in Plin5-null mice compared to WT littermates." (PMID 35624741, 2022). "Finally, we investigated whether dapagliflozin mediated the Plin5/PPARα signaling axis to exert a protective effect against cardiac hypertrophy." (PMID 34630108, 2021). "Initial research showed that myocardial-specific overexpression of Perilipin 5 promotes cardiac hypertrophy without impacting cardiac function." (PMID 40166465, 2025). "Furthermore, the mRNA levels of cardiac hypertrophy markers, such as ANF, BNF and β-MHC, were significantly upregulated in the myocardium in Plin5/leptin-DKO mice compared with Plin5-wild-type and leptin-deficient mice." (PMID 37667357, 2023). "We demonstrated that DAPA could activate the Plin5/PPARα signaling pathway and further significantly promoted the expressions PDK4 and HMGCS2 in cardiac hypertrophy." (PMID 34630108, 2021). "We suggested that DAPA mediated the Plin5/PPARα signal axis, and ultimately affected the expression level of PDK4 and HMGCS2, myocardial cell metabolism, and relieve the pathological progression of cardiac hypertrophy." (PMID 34630108, 2021). "In conclusion, we found that si-Plin5 and GW6471 could reverse the protective effect of dapagliflozin on cardiac hypertrophy." (PMID 34630108, 2021). "Therefore, we performed the present study to confirm the effect of DAPA towards cardiac hypertrophy in AAC-induced mice and to explore the regulatory effect on Plin5/PPARα signal axis." (PMID 34630108, 2021).
cardiac hypertrophy (continued). "A study involving Plin5 knockout mice found a significant increase in lactic acid accumulation, which, by inhibiting the pyruvate carrier (MPC), directed glucose towards lactate metabolism to drive myocardial cell hypertrophic growth, leading to severe myocardial hypertrophy." (PMID 40166465, 2025). "Earlier studies have shown that cardiomyocyte-specific overexpression of Plin5 promotes cardiac hypertrophy without compromising heart function, suggesting that Plin5 may be involved in mediating physiological hypertrophy." (PMID 36717246, 2023).
hepatocellular carcinoma (11 papers, 2019 to 2025). A malignant tumor that arises from hepatocytes. "PLIN5 has been reported to be promising prognostic or diagnostic markers in pancreatic cancer and hepatocellular carcinoma." (PMID 35223903, 2022). "Additionally, the prognostic value of PLIN5 has been explored in many cancers, including breast cancer, pancreatic cancer, hepatocellular carcinoma, and so on; however, we first investigated the prognostic role of mutated PLIN5 in patients with GC." (PMID 35223903, 2022). "Emphasizing the importance of LD junction deficiencies, PLIN5 dysfunction causes diseases such as neutral lipid storage disease (Section 5.2) and hepatocellular carcinoma (HCC) (Section 5.4)." (PMID 33143278, 2020). "In a recent study, we found a relation of PLIN5 to inflammation in human liver samples obtained from patients suffering from hepatocellular carcinoma (HCC)." (PMID 32481590, 2020). "In addition, PLIN5 has been extensively studied in the field of disease research, especially in hepatocellular carcinoma." (PMID 41300337, 2025). "Asimakopoulou’s study revealed that high PLIN5 expression was found in hepatocellular carcinoma and could be used as a biomarker for its diagnosis and treatment." (PMID 37189627, 2023). "In addition, there are only limited studies connecting PLIN5 to hepatocellular carcinoma (HCC), where PLIN5 expression is proven to be upregulated in hepatic tissue." (PMID 37108378, 2023).
myocardial ischemia (8 papers, 2019 to 2025). A disorder of cardiac function caused by insufficient blood flow to the muscle tissue of the heart. "In humans, genetic variation in PLIN5 is associated with impaired cardiac function after myocardial ischemia." (PMID 38397807, 2024). "In the mouse model of myocardial ischemia reperfusion injury, Plin5 deficiency aggravates the heart dysfunction, and similar results also were found in another myocardial ischemia model." (PMID 35401929, 2022). "However, during stress or myocardial ischemia, Plin5 deficiency results in myocardial reduced substrate availability, severely impaired cardiac function, and increased mortality." (PMID 38397807, 2024). "Thus, PLIN5 hampered expression is associated with a poorer outcome following myocardial ischemia and PLIN5 deficiency is related to increased oxidative stress in cardiomyocytes." (PMID 34680476, 2021). "Using lipidomics to analyze the heart tissues, a dramatic decrease in TG and DAG levels was observed in Plin5−/− mice compared to wild-type mice, and the heart function was reduced following myocardial ischemia or stress." (PMID 39859272, 2025). "After myocardial ischemia, FA oxidation was downregulated in Plin5−/− hearts, and changes were evident in the left ventricular diastolic volume, stroke volume, and ejection fraction." (PMID 39859272, 2025). "It has been reported that microRNA-370 mediated the Plin5-dependent PPAR signaling pathway to protect mice from myocardial ischemia/reperfusion injury." (PMID 34630108, 2021). "Moreover, Plin5 alleviates myocardial ischemia/reperfusion (MI/R) injury by reducing oxidative stress through increasing phosphorylation of PI3K/Akt to inhibit the lipolysis of LDs." (PMID 35401929, 2022). "This SNP led to reduced PLIN5 cardiac expression, impaired heart function, and adverse outcomes after myocardial ischemia, but it did not affect PLIN4 expression." (PMID 39859272, 2025).
Glucose intolerance (7 papers, 2019 to 2026). Glucose intolerance (GI) can be defined as dysglycemia that comprises both prediabetes and diabetes. "Notably, glucose intolerance was linked with changes in the ratio of adipose triglyceride lipase to perilipin 5 that is indicative of dysregulation of neutral lipid homeostasis." (PMID 38656127, 2024). "Notably, glucose intolerance was associated with changes in the ratio of adipose triglyceride lipase to perilipin 5 in the LD proteome, suggesting dysregulation of neutral lipid homeostasis in glucose-intolerant fatty liver." (PMID 38656127, 2024). "With glucose intolerance seen in old SA male mice, we probed additional genes that potentially impact glucose tolerance and reported to be regulated by PLIN5 in other tissues and cultured cells." (PMID 40238664, 2025). "The protection role of PLIN5 in β-cell function observed in cell experiments were further verified in in vivo study indicated by mitigated glucose intolerance in high fat diet fed mice with β-cell-specific overexpression of PLIN5." (PMID 31384284, 2019). "Acute BAT PLIN5 knockout causes cold intolerance but not glucose intolerance." (PMID 41509390, 2026). "Notably, Plin5-Tg mice were less obese and protected from glucose intolerance on HFD." (PMID 37150323, 2023). "However, mice with constitutive knockout of Plin5 in BAT did not exhibit cold or glucose intolerance likely explained by the induction of beiging genes in iWAT with compensatory beige adipocyte thermogenesis." (PMID 41509390, 2026).
non-alcoholic fatty liver disease (7 papers, 2012 to 2025). "On the contrary, hepatocyte-derived LCN2 protects against diet-induced nonalcoholic fatty liver disease by regulating lipolysis, fatty acid oxidation, de novo lipogenesis, and apoptosis or by interfering with expression of the lipid droplet associate protein Perlipin 5 (PLIN5)." (PMID 32718038, 2020). "This is consistent with the function played by PLIN5 in non-alcoholic fatty liver disease (NAFLD) liver disease, specifically overexpression of PLIN5 in activated HSCs inhibition of cell proliferation, and a significant increase in cell apoptosis." (PMID 41300337, 2025). "So far, research has focused on the role of PLIN5 in the context of non-alcoholic fatty liver disease (NAFLD) and specifically in lipid droplet formation and lipolysis, where PLIN5 serves as a regulator of lipid metabolism." (PMID 37108378, 2023).